NAT10 (N-acetyltransferase 10)
Description:
RNA cytidine acetyltransferase that catalyzes the formation of N(4)-acetylcytidine (ac4C) modification on mRNAs, 18S rRNA and tRNAs. Catalyzes ac4C modification of a broad range of mRNAs, enhancing mRNA stability and translation. mRNA ac4C modification is frequently present within wobble cytidine sites and promotes translation efficiency. Mediates the formation of ac4C at position 1842 in 18S rRNA. May also catalyze the formation of ac4C at position 1337 in 18S rRNA (By similarity). Required for early nucleolar cleavages of precursor rRNA at sites A0, A1 and A2 during 18S rRNA synthesis. Catalyzes the formation of ac4C in serine and leucine tRNAs (By similarity). Requires the tRNA-binding adapter protein THUMPD1 for full tRNA acetyltransferase activity but not for 18S rRNA acetylation. The relevance of the protein lysine acetyltransferase activity is however unsure in vivo. Activates telomerase activity by stimulating the transcription of TERT, and may also regulate telomerase function by affecting the balance of telomerase subunit assembly, disassembly, and localization. Involved in the regulation of centrosome duplication by acetylating CENATAC during mitosis, promoting SASS6 proteasome degradation. Part of the small subunit (SSU) processome, first precursor of the small eukaryotic ribosomal subunit. During the assembly of the SSU processome in the nucleolus, many ribosome biogenesis factors, an RNA chaperone and ribosomal proteins associate with the nascent pre-rRNA and work in concert to generate RNA folding, modifications, rearrangements and cleavage as well as targeted degradation of pre-ribosomal RNA by the RNA exosome.
Synonyms: hALP; ALP; KIAA1709; FLJ10774; FLJ12179; NET43; Kre33
Tractability: Small molecule: a structure with a bound ligand is known. PROTAC: ubiquitination databases record sites on it; its protein half-life has been measured; a small molecule that binds it is known.
Target class: Enzyme; Transferase
Gene: Protein-coding gene on chromosome 11 (34,105,608 to 34,147,670, forward strand). Ensembl gene ENSG00000135372.
Subcellular location: Nucleus, nucleolus; Midbody
Subcellular location (Human Protein Atlas): Nucleoli; Midbody
Pathways (Reactome):
Metabolism of RNA: rRNA modification in the nucleus and cytosol
Gene Ontology:
Molecular function: 18S rRNA cytidine N-acetyltransferase activity; DNA polymerase binding; mRNA N-acetyltransferase activity; N-acetyltransferase activity; protein binding; RNA binding; tRNA cytidine N4-acetyltransferase activity; acyltransferase activity, transferring groups other than amino-acyl groups; ATP binding; catalytic activity, acting on a nucleic acid
Biological process: negative regulation of telomere maintenance via telomerase; positive regulation of translation; protein acetylation; regulation of centrosome duplication; regulation of translation; ribosomal small subunit biogenesis; maturation of SSU-rRNA; rRNA acetylation involved in maturation of SSU-rRNA; rRNA modification; tRNA acetylation; tRNA wobble cytosine modification; rRNA metabolic process
Cellular component: chromosome, telomeric region; membrane; midbody; nucleolus; small-subunit processome; telomerase holoenzyme complex; nucleoplasm; nucleus
Genetic constraint (gnomAD): Loss-of-function variants: 96 observed, 121.6 expected, observed/expected ratio (o/e) 0.79, 90% interval 0.67 to 0.94. The upper end of that interval is the gene's LOEUF score, 0.94, which puts it in group 3 of 6, group 1 being the genes least tolerant of losing a copy. Missense variants: 1,083 observed, 1,224 expected, observed/expected ratio (o/e) 0.88, 90% interval 0.84 to 0.93. Synonymous variants: 449 observed, 468.97 expected, observed/expected ratio (o/e) 0.96, 90% interval 0.88 to 1.03.
Homologues: Orthologues: macaque NAT10 (99% identical), chimpanzee NAT10 (98% identical), pig NAT10 (96% identical), dog NAT10 (96% identical), mouse Nat10 (95% identical), rat Nat10 (95% identical), guinea pig NAT10 (94% identical), rabbit NAT10 (94% identical), tropical clawed frog nat10 (81% identical), zebrafish nat10 (80% identical), Caenorhabditis elegans nath-10 (54% identical), Drosophila melanogaster l(1)G0020 (52% identical).
Diseases named in the same sentence as NAT10 in open-access papers:
NAT10 is named in the same sentence as 174 diseases in open-access papers, as found by Europe PMC text mining. Sharing a sentence is not in itself a finding about the gene and the disease. The quoted sentences say what the papers report.
gastric cancer (54 papers, 2021 to 2026). A primary or metastatic malignant neoplasm involving the stomach. "In this study, the molecular mechanism underlying DARS-AS1/miR-330-3p/NAT10-regulated gastric cancer was probed." (PMID 36568518, 2022). "Moreover, as an ac4C-modified acetyltransferase, NAT10 is implicated in several other cancers, including pancreatic cancer, stomach cancer, bladder cancer, and cervical cancer." (PMID 41316475, 2025). "NAT10 is implicated in tumor metabolic reprogramming and plays a critical role in the progression, metastasis, and drug resistance of various malignant tumors, including gastric cancer." (PMID 40951343, 2025). "NAT10 is also associated with other malignant diseases, such as breast cancer (BC), gastric cancer (GC), and colorectal cancer (CRC)." (PMID 39817252, 2025). "On the contrary, knockdown of NAT10 enhances the sensitivity of cisplatin-resistant gastric cancer cells to cisplatin, both in vitro and in vivo." (PMID 41956987, 2026). "NETosis promote gastric cancer metastasis by increasing NAT10‐mediated N4‐acetylcytidine modification of SMYD2 mRNA, which stabilises SMYD2 and enhances cancer cell invasion and migration." (PMID 41503514, 2026). "Taken together, these findings offer novel insights into the role and mechanism of NAT10 in the crosstalk between cisplatin chemoresistance and immunosuppression in gastric cancer." (PMID 41956987, 2026). "NAT10 thus holds promise as a highly attractive target, with the potential to synergize with PD-1-based immunotherapy to reverse cisplatin resistance in gastric cancer." (PMID 41956987, 2026). "Here, we observed that elevated NAT10 levels promote cisplatin chemoresistance in gastric cancer cells." (PMID 41956987, 2026). "The combination of a NAT10 inhibitor and an anti-PD-1 antibody synergistically enhances the antitumor efficacy against cisplatin- resistant gastric cancer cells in murine models." (PMID 41956987, 2026). "Specifically, NAT10 was found to be significantly upregulated in gastric cancer, enhancing cell proliferation, migration, invasion, and the growth of patient‐derived organoids, ultimately accelerating tumor progression." (PMID 39764566, 2025). "In gastric cancer, NAT10 directly interacts with the 3′UTR of COL5A1 mRNA, modulating its ac4C modification." (PMID 40881352, 2025). "This is consistent with the results of previous studies on the high expression of NAT10 in bladder cancer, gastric cancer, pancreatic cancer and other tumours." (PMID 40169553, 2025). "NAT10 is reported to promote gastric cancer metastasis by regulating ac4C acetylation on 3’UTR mRNA of COL5 A1, which is a marker of EMT, to maintain its mRNA stability and further promotes EMT indirectly." (PMID 40588654, 2025). "Previous researches have indicated that NAT10 plays a significant part in various malignant tumors, including cervical cancer 14, gastric cancer 13, and bladder cancer." (PMID 40303290, 2025). "In gastric cancer, NAT10 stimulates the HIF-1 pathway and alters glucose metabolism through ac4C modification of SEPT9 mRNA." (PMID 40881352, 2025). "In gastric cancer, NAT10-mediated SRSF2 stabilization induces exon skipping in YTHDF1 pre-mRNA, creating a truncated m6 A reader isoform that promotes tumor progression." (PMID 40588654, 2025). "For example, NAT10-mediated ac4C modification directly targets COL5A1, with NAT10 promoting gastric cancer metastasis." (PMID 40303290, 2025). "Recent studies have found that NAT10 is abnormally highly expressed in gastric cancer tissues, significantly promoting the metastasis and invasion of gastric cancer cells." (PMID 39764566, 2025).
gastric cancer (continued). "Under hypoxia, HIF-1α-induced NAT10 stabilizes SEPT9 mRNA via ac4C modification, forming a NAT10/SEPT9/HIF-1α feedback loop that drives glycolysis addiction in gastric cancer." (PMID 40999468, 2025). "Emerging evidence links NAT10-mediated ac4C modification to the pathogenesis of numerous disorders like gastric cancer, osteoporosis, and cardiac fibrosis." (PMID 40362562, 2025). "In gastric cancer, NAT10 engages with the splicing factor serine/arginine-rich splicing factor 2 (SRSF2), instigating its acetylation and subsequent stabilization." (PMID 40588654, 2025). "DARS-AS1 upregulates the expression of NAT10 by competitively binding to miR-330-3p, thereby impairing the viability and invasive potential of gastric cancer cells." (PMID 41316475, 2025). "In gastric cancer, both ac4C mRNA modification and its regulator, NAT10, are elevated, correlating with disease progression and poor prognosis." (PMID 39791162, 2025). "The interaction between gastric cancer cells and NETs, which boosts cell viability, migration, and invasion, is influenced by NAT10 and Set and MYND domain containing 2(SMYD2)." (PMID 39791162, 2025). "The regulatory role of NAT10 in tumor metastasis and cell motility was reported in gastric cancer, head and neck squamous cell carcinoma, prostate cancer, oral squamous cell carcinoma and esophageal squamous cell carcinoma." (PMID 40588654, 2025). "This consistent approach demonstrates the importance of NAT10 in regulating gastric cancer malignancy progression through glucose metabolic homeostasis." (PMID 39990211, 2025). "As the only known “writer” protein for ac4C synthesis, NAT10 is upregulated in a variety of malignant tumours such as gastric cancer, bladder cancer, colorectal cancer, bladder cancer and involved in poor prognoses." (PMID 38961519, 2024). "NAT10 plays an essential role in regulating tumorigenesis, including gastric cancer, colorectal cancer and breast cancer." (PMID 38308713, 2024). "Knocking out NAT10 in human gastric cancer AGS cells reduces ac4C modification of total RNA and mRNA and represses proliferation and invasion of tumor cells." (PMID 38233930, 2024). "In gastric cancer progression, NAT10 modifies MDM2 mRNA with ac4C acetylation to stabilize MDM2 mRNA, resulting in its up-regulation and down-regulation of p5346." (PMID 38459019, 2024). "Consistently, previous studies reported that NAT10 can regulate the MDM2 mRNA stability in gastric cancer." (PMID 38331765, 2024). "To evaluate the oncogenic role of NAT10 in gastric cancer in vivo, we applied both a subcutaneous xenograft model and a peritoneal dissemination model." (PMID 36609449, 2023). "We found that NAT10 was overexpressed in many types of tumour tissues including gastric cancer, colon cancer, rectal cancer, B-cell lymphoma, and thymic carcinoma." (PMID 36908042, 2023). "In the present study, we demonstrated that both the ac4C mRNA modification and its regulator NAT10 are increased in gastric cancer, and increased NAT10 expression correlates with disease progression and poor patient prognosis." (PMID 36609449, 2023). "Previous studies have reported that NAT10 is closely correlated with disease progression in a variety of human tumours, including stomach cancer, prostate cancer, and bladder cancer." (PMID 36908042, 2023).
gastric cancer (continued). "In relation to cancers, NAT10 reportedly promotes tumor progression in hepatocellular carcinoma, breast cancer, gastric cancer, head, and neck squamous cell carcinoma, and bladder cancer." (PMID 36522719, 2022). "Rescue experiments verified the effect of DARS-AS1–miR-330-3p–NAT10 interaction on cellular abilities in gastric cancer cells." (PMID 36568518, 2022). "In conclusion, DARS-AS1 was elevated in gastric cancer, and DARS-AS1/miR-330-3p/NAT10 signaling offered some new horizons for predicting prognosis and a novel therapeutic method for the treatment of gastric cancer." (PMID 36568518, 2022). "According to the most recent report, the high expression of the mRNA ac4C writer NAT10 indicates poorer prognosis of various malignancies and NAT10‐mediated ac4C modification on mRNA promotes gastric cancer metastasis and EMT." (PMID 35522942, 2022). "Other researchers have found that NAT10 plays a vital function in gastric cancer metastasis by regulating the writing pathway of the gastric cancer mRNA ac4C." (PMID 36360287, 2022). "DARS-AS1 acts as a competitive endogenous RNA to regulate the NAT10 expression by sponging miR-330-3p in gastric cancer cells." (PMID 36568518, 2022). "Additionally, NAT10 was found to increase the ability of gastric cancer cells to adhere to hepatocytes via ac4C modification of KLF5 mRNA, leading to increased transcription of ITGαV." (PMID 39985269, 2025). "Additionally, NAT10-mediated acetylation enhances the hypoxia tolerance of gastric cancer cells by increasing their glycolytic dependency." (PMID 39791162, 2025). "This mutual amplification mirrors feedback loops observed in other cancers, such as the NAT10/SEPT9/HIF-1α axis in gastric cancer glycolysis and the NAT10/KIF23/GSK-3β axis in colorectal cancer progression, underscoring the critical role of NAT10 in sustaining oncogenic signaling networks." (PMID 40999468, 2025). "Moreover, NAT10 has been shown to contribute to the malignant progression of tumors in gastric cancer, cervical cancer and osteosarcoma by promoting glycolysis." (PMID 41426311, 2025). "Moreover, NAT10 promotes gastric cancer by regulating COL5A1, and promotes bladder cancer progression by participating in DNA damage repair pathways." (PMID 40169553, 2025). "In gastric cancer, NAT10 promotes tumor metastasis by stabilizing ac4C modification on COL5A1 mRNA." (PMID 41426311, 2025). "The NAT10 inhibitor Remodelin could synergize with the YAP1 inhibitor Verteporfin to fuel immune checkpoint blockade in gastric cancer." (PMID 40860183, 2025). "DARS‐AS1/miR‐330‐3p/NAT10 regulates progression of gastric cancer." (PMID 39640362, 2024). "Notably, recent studies suggest that NAT10 promotes the progression of gastric cancer via ac4C modification of COL5A1." (PMID 38182571, 2024). "For instance, NAT10 facilitates gastric cancer metastasis through N4-acetylated COL5A1." (PMID 38243170, 2024). "NAT10‐mediated COL5A1 acetylation promotes gastric cancer metastasis." (PMID 39640362, 2024). "NAT10/SEPT9/HIF‐1α positive feedback loop regulates glucose metabolism in gastric cancer." (PMID 39640362, 2024). "NAT10 promotes the progression of gastric cancer and pancreatic cancer." (PMID 38182571, 2024). "NAT10 mediates ac4C acetylation of SMYD2 to promote progression of gastric cancer." (PMID 39640362, 2024). "Together, these data demonstrate that pharmacological inhibition of NAT10 may provide a promising treatment for gastric cancer." (PMID 36609449, 2023). "Bioinformatics analysis shows that DARS-AS1/miR-330-3p/NAT10 interaction may be involved in the tumorigenesis of gastric cancer." (PMID 36568518, 2022). "A recent study reported that NAT10 expression was increased and associated with poor prognosis, as well as had crucial effects on tumor metastasis and cell epithelial-to-mesenchymal transition (EMT) in gastric cancer." (PMID 36568518, 2022).